CXCR4 (C-X-C motif chemokine receptor 4)
Diseases named in the same sentence as CXCR4 in open-access papers (continued):
Sharing a sentence is not in itself a finding about the gene and the disease.
leukemia (continued). "CXCL12 binds and activates its homologous receptor CXCR4 in the microenvironment of the bone marrow to mediate the transport of leukemia cells, while keeping in close contact with stromal cells and the extracellular matrix to generate growth-promoting and anti-apoptotic signals." (PMID 33381455, 2020). "MSC in other leukaemia models had also been associated with leukemic cells survival during chemotherapy; this is due in part to migration of leukemic cells beneath MSC, a phenomenon that has been associated with the expression of functional CXCR4." (PMID 32466311, 2020). "Because we found that CXCL12 is dispensable for AML development, we next assessed whether UBIQUITIN or MIF promotes growth and survival of MLL-AF9 leukemia cells by binding to CXCR4." (PMID 32460032, 2020). "Moreover, increased Gr-1 expression following disruption of Cxcr4 in leukemia cells in vivo was abolished by expression of Cxcr4WT or Cxcr4D99G but not by the signaling-dead variant, Cxcr4L251P." (PMID 32460032, 2020). "To address whether MIF promotes leukemia cells in a CXCR4-dependent manner, we evaluated whether leukemia cells with Cxcr4 disruption responded to MIF." (PMID 32460032, 2020). "Changes in the SDF-1/CXCR4 axis may contribute to the weakening of the interaction of leukemia cells with the bone marrow stroma, responsible for the presence of chemoresistance, MRD, and an increase in the risk of recurrence." (PMID 32580317, 2020). "Because migration is necessary for infiltration and consequent relapse of leukemia, it would be interesting to explore whether RhoGDI2 brakes CXCR4-mediated T-ALL infiltration in vivo." (PMID 32903764, 2020). "Although we found that Cxcr4 disruption results in increased ROS and differentiation of leukemia cells, it is currently unclear whether it is elevated ROS levels that cause differentiation of the cells." (PMID 32460032, 2020). "Furthermore, the interaction between stromal cell-derived factor-1 (SDF-1 or CXCL12) and chemokine receptor type 4 (CXCR4) is crucial for the migration and adhesion of leukemia cells to the bone marrow stroma." (PMID 32580317, 2020). "Although CXCR4 expression was essential for serial propagation of MLL-AF9 leukemia cells in mice, it is unclear whether CXCR4 is critical for initiation of MLL-AF9 leukemia in a primary recipient mouse." (PMID 32460032, 2020). "Interestingly, the leukemia cells in these two mice expressed normal CXCR4 levels in the bone marrow and spleen, suggesting that the cells had escaped silencing." (PMID 32460032, 2020). "Aberrant CXCR4/CXCL12 signaling is associated with a variety of pathophysiological conditions including cancer metastasis, enhanced tumor growth, chronic inflammation, leukemia and altered immune responses." (PMID 32994431, 2020). "CXCR4 has been shown to play a key role in normal HSCs in the bone marrow niche and has been explored as a therapeutic target in leukemia." (PMID 32460032, 2020). "In addition, consistent with the increased phosphorylation of NF-κB upon Cxcr4 disruption, overexpression of Cxcr4WT in Cxcr4-disrupted leukemia cells resulted in reduced phosphorylation of NF-κB." (PMID 32460032, 2020). "Importantly, CXCR4 mRNA electroporated NK cells had preserved high cytotoxic function against leukemia, lymphoma, and multiple myeloma cell lines as assessed by CD107a degranulation." (PMID 31231387, 2019). "Overall, these findings can suggest that Notch and CXCR4 could converge on metabolic pathways to further sustain leukemia progression but also unveil a new therapeutic target that may be common to B- and T-ALL." (PMID 31346528, 2019). "We compared the protein expression level of p-STAT5/STAT5, Pim-1 and CXCR4 among the FLT3-ITD-mutated, FLT3-wt and normal control groups using Western blotting to further examine whether CXCR4 expression in leukemia cells is regulated by FLT3-ITD mutations." (PMID 31434952, 2019).
leukemia (continued). "The RFI of CXCR4 expression on bone marrow leukemia cells was 6.31 ± 6.01 (median ± SD), as assessed using flow cytometry, and the value was significantly higher than control cells (1.19 ± 0.21, P ≤ 0.0001), indicating that CXCR4 expression was upregulated." (PMID 31434952, 2019). "Moreover, CXCR4 play a major role in leukemia initiating activity and T-ALL propagation in vivo, by modulating not only cell motility but also survival and proliferation in T-ALL cells." (PMID 31346528, 2019). "Furthermore, CXCR4 regulates BM retention of both leukemias, but is redundant in fine‐tuning leukemia‐supporting interactions between parenchymal AML cells and the BM microenvironment." (PMID 30422351, 2019). "CXCR4 expression was found to be essential for T-ALL maintenance and progression with loss of CXCL12/CXCR4 signaling leading to reduced Myc expression (a transcription factor directly regulated by NOTCH1) and previously linked to leukemia initiating cell activity in T-ALL." (PMID 29666622, 2018). "We previously reported that uPAR and CXCR4 can be regulated by common microRNAs in leukemia cells." (PMID 29963240, 2018). "Likewise, in mouse models of acute myeloid leukemia CXCR4 antagonism mobilized leukemia cells out of the bone marrow niches and, at the same time, enhanced chemosensitivity." (PMID 30622535, 2018). "Mechanistically, bone marrow mesenchymal cells have been demonstrated to upregulate a signaling complex in the leukemia cells comprising CXCR4 and activating pro-survival signals via extracellular signal-related kinase 1/2 (ERK1/2) and the phosphoinositide 3-kinase (PI3K)/Akt pathway." (PMID 30622535, 2018). "CXCL12/CXCR4 signaling axis promotes cell survival and proliferation and may contribute to the tropism of leukemia cells towards lymphoid tissues and bone marrow." (PMID 28526063, 2017). "Of great interest is the up-regulation of CXCR4 in ATL1102 treated leukemia cells." (PMID 29117236, 2017). "Additionally, in-vitro-derived CXCR4+ NK cells have been shown to migrate to the BM in murine models of leukemia." (PMID 28915651, 2017). "Furthermore, CXCR4 expression in leukemia and lymphoma cell lines including K562, MEC1, Namalwa, Raji, JeKo-1, and Jurkat showed a broad range of expression levels, with ΔMFIs of −2.35, 0.01, 73.41, 526.72, 725.45, and 1358.5, respectively." (PMID 28526063, 2017). "In addition, we demonstrate that PF-06747143 monotherapy treatment potently reduces leukemia burden in PB, BM, and spleen in AML PDX models expressing low and high levels of CXCR4 and this is associated with increased survival." (PMID 28779088, 2017). "The CXCR4 ligand (CXCL12) stimulates CXCR4 promoting cell survival and proliferation, and may contribute to the tropism of leukemia cells towards lymphoid tissues." (PMID 26646452, 2016). "The use of CXCR4 antagonists may provide a novel therapeutic approach to interrupt these protective interactions and sensitize leukemia cells to chemotherapy in vivo." (PMID 27429863, 2015). "The SDF-1/CXCR4 signaling pathway regulates leukemia cell adhesion and migration." (PMID 26652601, 2015). "Interestingly, CCR7 that regulates CNS infiltration in T-ALL and CXCR4, which is essential for stem cell and leukemia cell localization were both repressed upon KLF4 overexpression in Jurkat cells." (PMID 25644173, 2015). "We then verified whether blocking the SDF-1/CXCR4 signaling pathway could influence the adhesion between leukemia and stromal cells." (PMID 26652601, 2015). "Our experimental results demonstrated that the drug AMD3100 could downregulate the CXCR4 expression in leukemia cell and influence the adhesion and migration of leukemia cells." (PMID 26652601, 2015). "All these results indicated that blocking the signaling pathway of SDF-1/CXCR4 through drug treatment could successfully affect the adhesion ability of leukemia cells on stromal cells." (PMID 26652601, 2015).
leukemia (continued). "Therefore, it is very necessary and of great significance to develop novel peptides targeting CXCR4 for providing more therapeutic options in leukemia treatments." (PMID 25312253, 2014). "Furthermore, the selective blocking of the CXCR4 by plerixafor overcome the protective effect of the bone marrow environment for BCR-ABL(+) leukemia." (PMID 20569497, 2010). "Moreover, CXCR4 expression was found to be increased in several malignancies including gliomas, breast tumors, certain leukemia cell lines, uterine cancer, Burkitt's lymphoma, neuroblastomas, and pancreatic cancer." (PMID 19340288, 2009). "Moreover, we demonstrate that T22-PE24-H6 treatment potently reduces leukemia burden in the BM and liver with no associated toxicity in a CXCR4+ disseminated AML model." (PMID 36986589, 2023). "Thus, for the first time we are showing that the presence of both sGRP78 and CXCR4 are associated with High-risk leukemia at diagnosis but not with Standard-risk leukemia." (PMID 35149705, 2022). "Similarly, exosomes carry Fas ligand (FAS-L), NPM1, FLT3, matrix metallopeptidase 9 (MMP9), insulin-like growth factor type 1 receptor (IGF1-R), CXCR4, and chaperones to alter the BM microenvironment and to improve the survival of leukemia cells, especially LSCs." (PMID 35865470, 2022). "Thus, sGRP78+ leukemia cells can be detected in blood and together with the expression of CXCR4." (PMID 35149705, 2022). "By using a combination of flow cytometry and high multidimensional analysis, we found a distinctive cluster containing high levels of sGRP78, CD10, CD19, and CXCR4 in bone marrow samples obtained from High-risk leukemia patients, which was absent in the compartment of Standard-risk leukemia." (PMID 35149705, 2022). "Indeed, Crazzolara and colleagues reported a correlation between high CXCR4 expression on leukemic cells and extramedullary organ infiltration, whilst Kato and colleagues, using a xenograft mouse model, have demonstrated that liver dissemination of leukemia is driven by the CXCL12/CXCR4 axis." (PMID 35884364, 2022). "CXCL12/CXCR4 could induce the chemoresistance of leukemia cells." (PMID 33743810, 2021). "Similarly, CXCR4 signaling in leukemia enhances invasion and induces therapy resistance." (PMID 33096815, 2020). "Importantly, these findings also show that depletion of leukemia cells following Cxcr4 disruption is on target and not caused by off-target effects of the Cxcr4 sgRNA." (PMID 32460032, 2020). "We infer that SDF‐1/ CXCR4 axis may help the leukemia cells escape from the attack of the chemotherapy drugs by intrinsic immune regulation, including promoting the proliferation and secretion of cytokines to inhibit cell apoptosis, decreasing the sensitivity to chemotherapy." (PMID 31518054, 2019). "Indeed, CXCR4 overexpression is associated with extramedullary infiltration in many hematological malignancies, and our study indicated that the FLT3-ITD MR was positively correlated with the RFI for CXCR4 expression on leukemia cells." (PMID 31434952, 2019). "Consequently, CXCR4 has garnered significant interest as a therapeutic target and small-molecule CXCR4 antagonists have emerged as attractive agents for the treatment of several carcinomas, leukemias, and lymphomas." (PMID 29682200, 2018). "Furthermore, our differentiated NK cells expressed high levels of CXCR4, which could guide these cells to eliminate leukemia cells residing in the BM." (PMID 28915651, 2017). "Thus, blockade of CD82 might augment the levels of MMP9 and CXCR4, resulting in mobilization of leukemia cells into the peripheral circulation." (PMID 26139471, 2015). "Various cancers including glioma, neuroblastoma, and leukemia show overexpression of CXCR4 and since their blockade may have implications for therapy several inhibitors have been developed and are, at least for hematopoietic cancers, being tested in clinical trials." (PMID 26998479, 2015).
leukemia (continued). "Thus, CXCR4 targeting has been a treatment strategy against leukemia and solid tumors." (PMID 27429863, 2015). "Hence CXCR4 antagonists were developed for leukemia therapy." (PMID 26538086, 2015). "Cells with higher surface CXCR4 upregulation also had greater differences between the Protective and Reversal Index, suggesting that plerixafor diminishes stromal protection more effectively in leukemias that highly upregulate surface CXCR4 in response to chemotherapy." (PMID 25333254, 2014). "Finally, combining FLT3 and CXCR4 inhibitors could overcome stromal protection of FLT3-activated leukemia cells and could be additive to any of the approaches above." (PMID 25295230, 2014). "Finally, we hypothesized that CXCR7 potentiates CXCR4 response and may contribute to the maintenance of leukemia by initiating cell recruitment to bone marrow niches that were once occupied by normal hematopoietic stem cells." (PMID 24497931, 2014). "Therefore, targeting the CXCR4/CXCL12 axis is attractive therapeutic approach in leukemia patients." (PMID 20049170, 2010). "Moreover, playing CXCR4 a key role in cross-talk between leukemia cells and their microenvironment, the potential use of this drug in hematological cancer has been widely studied and it is currently used in clinics for the mobilization of hematopoietic stem cells." (PMID 20049170, 2010). "Plerixafor, as a targeted CXCR4 inhibitor (FDA-approved), mobilizes leukemia cells post-hematopoietic cell transplantation, sensitizing them to cytotoxic therapy and enhancing healthy donor stem cell engraftment." (PMID 40427609, 2025). "This system, that targets both CXCR4 and CD44 receptors, achieved significant inhibition of leukemia blast proliferation and metastatic dissemination in an AML xenograft model." (PMID 40307933, 2025). "CXCR4 and its ligand, SDF-1, constitute a critical axis in AML, involved in the navigation and maintenance of leukemia cells within the bone marrow niche, a sanctuary that offers protection and sustenance to both malignant and healthy hematopoietic stem cells." (PMID 39871937, 2024). "The CXCL12/CXCR4/ACKR3 axis plays a pivotal role in regulating the migration, dissemination, and homing of leukemia cells." (PMID 38920657, 2024). "Multiple studies have demonstrated that within leukemia, the CXCL12/CXCR4 axis plays a pivotal role in maintaining the interactions between leukemia cells and the bone marrow niche." (PMID 38920657, 2024). "Reviews have highlighted that the CXCL12/CXCR4/ACKR3 axis can activate the STAT3 pathway, leading to leukemia development." (PMID 38920657, 2024). "By binding to C-X-C chemokine receptor type 4 (CXCR4), SSL10 inhibits the migration of leukaemia cells." (PMID 38062361, 2023). "This drug blocks CXCR4 and opposes CXCL12 stimulation of chemotaxis and cell proliferation pathways in leukemia cells." (PMID 38313431, 2023). "They conjugated RBCEVs with a cyclic peptide to specifically target CXCR4 or with a monoclonal antibody anti-CD33 to promote the specific binding and uptake of the conjugated EVs by leukemia cells expressing the corresponding receptors." (PMID 36839687, 2023). "CXCL14, a natural inhibitor of the CXCL12-CXCR4 axis, specifically bound to CXCR4 with high affinity and inhibited CXCL12-mediated chemotaxis and migration of human bone marrow-derived hematopoietic progenitor cells and leukemia-derived cells." (PMID 37497001, 2023). "We first validated CXCR4 and ITGB1 which are well-known to influence the leukemia-niche interaction and dropped out in both ALL samples." (PMID 37422628, 2023). "Blocking the interaction between CXCR4/CXCL12 effectively compromised the homing of LSCs into the BM niche and rendered leukemia cells sensitive to chemotherapy." (PMID 35865470, 2022). "The leukemia cells of M5 patients with EMI showed low expression of miR-3677-5p but high expression of the mRNA of CXCL12 and CXCR4." (PMID 36569343, 2022).
leukemia (continued). "Meanwhile, our results showed that patients' leukemia cells in the EMI group showed abnormally high expression of CXCL12 and CXCR4 mRNA." (PMID 36569343, 2022). "One of them used a more stringent sorting approach to profile the transcriptome of leukemia initiating cells and reported increased BCL2 and CXCR4 signaling in relapse." (PMID 35986270, 2022). "Thus, the evaluation of sGRP78+CXCR4+ markers along with CD10 and CD19 in leukemic pediatric samples at diagnosis could contribute to a better categorization of High and Standard-risk pediatric leukemia." (PMID 35149705, 2022). "To date, CXCR4 antagonists such as AMD3465 or AMD3100 (plerixafor) were developed as a strategy to reduce leukemia burden and infiltration by disrupting the CXCL12/CXCR4 interaction." (PMID 36428753, 2022). "Collectively, these results indicate that SDF‐1/CXCR4 regulates the migration and chemosensitivity of ALL cells and their homing to BM and enhances the interaction between leukaemia cells and the extracellular matrix." (PMID 34050566, 2021). "CXCR4 antagonists inhibited the chemotaxis and migration of B‐ALL cell lines and leukaemia blasts to BM stroma." (PMID 34050566, 2021). "CXCR4 is also highly expressed in T-ALL cells, reporting also CXCR7 as the second receptor for CXCL12 that is able to augment CXCR4 response in ALL, therefore contributing to leukemia maintenance by initiating cell recruitment to BM niches." (PMID 34026651, 2021). "The CXCL12/CXCR4 pathway is involved in homing of T-ALL cells to the bone marrow and in Leukemia Initiating Cell (LIC) activity." (PMID 34394130, 2021). "The studies presented here are limited by the use of cell lines, and future studies examining CXCR4 expression and the use of CXCR4 inhibitors in patient samples will add valuable insight to the biology of CALM-AF10 leukemia." (PMID 35070954, 2021). "Many chemokine axes such as CXCL12/CXCR4 and CCL25/CCR9 have been proved to play important roles in leukemia microenvironment and further affect ALL outcomes." (PMID 33743810, 2021). "Among factors regulating leukemia-MSC interactions, CXCL-12/CXCR4 axis plays a central role in leukemia resistance to therapies." (PMID 34771483, 2021). "The essential roles of the CXCL12/CXCR4 axis in niche positioning and cell cycle status of leukemia stem cells have been highlighted by the specific deletion of CXCL12 from BM MSCs, suggesting the differential use of CXCL12-niches by CXCR4+ malignant cells." (PMID 34737747, 2021). "Immunofluorescence microscopy further revealed that CXCR4 was primarily localized at the plasma membrane, to a greater degree in CALM-AF10 translocated leukemias." (PMID 35070954, 2021). "When analyzing the effects of a CXCR4 inhibitor, we found that AMD3465 treatment decreased the migration of CALM-AF10 translocated leukemias." (PMID 35070954, 2021). "As SFK can act on several pathways, we chose to analyze pathways that are abnormally activated in leukemia cells and involved in cell motility, migration and chemotaxis, and that is described as in CXCL12/CXCR4 signaling." (PMID 33842460, 2021). "High expression of CXCR4 by leukemic blasts and activation of the CXCL12/CXCR4 axis are involved in leukemia migration." (PMID 33743810, 2021). "MLL +ALL cells expressed both CXCR4 and CXCR7, but chemotherapeutic agent‐induced apoptosis of leukaemia cells was inhibited by pretreatment with a CXCR4 inhibitor and accelerated by pretreatment with a CXCR7 inhibitor." (PMID 34050566, 2021). "Using both human and mouse cell line models, we examine the relationship between CXCR4 expression and phenotype in CALM-AF10 transformed leukemias." (PMID 35070954, 2021). "Additional in vivo studies are needed to definitively establish the relationship between CXCR4 expression and extramedullary disease development in CALM-AF10 leukemia." (PMID 35070954, 2021).